FOXP3 (forkhead box P3)
Diseases named in the same sentence as FOXP3 in open-access papers (continued):
Sharing a sentence is not in itself a finding about the gene and the disease.
tumor (continued). "Specific subpopulations of T cells in sham or tumor-bearing hemispheres were detected by staining with antibodies against CD8, CD4 and intracellular FOXP3; MDSCs were detected by staining with anti-CD11b and anti-Gr1 antibodies." (PMID 29242629, 2017). "Other sensitive indicators for monitoring immune function within tumor microenvironment are the ratios of immune effector T cells (CD3+ and CD8+) to immune suppressor T cells (FOXP3+): CD3+/FOXP3+ and CD8+/FOXP3+." (PMID 28885584, 2017). "Tumor-infiltrating CD4+ and CD25+ cells were also present, but importantly, FoxP3+ Treg cells were only a minor subfraction of the tumor immune cell infiltrate." (PMID 29244745, 2017). "As well as in other solid tumors, forkhead box P3 (FOXP3) + T-regs, a subset of CD4+ T cells specialized in the suppression of the host immune system against self antigens, promotes tumor development inducing a state of severe immune-suppression in HCC." (PMID 28420805, 2017). "Here, we show that lnc-epidermal growth factor receptor (EGFR) upregulation in Tregs correlates positively with the tumour size and expression of EGFR/Foxp3, but negatively with IFN-γ expression in patients and xenografted mouse models." (PMID 28541302, 2017). "Tumor-infiltrating CD4+, CD8+ T and NKT cells increased after MART1 plasmid + AdMGshT, instead, tumor-infiltrating CD4+CD25+FoxP3+ regulatory T cells were decreased." (PMID 28178658, 2017). "The median numbers of tumor-infiltrating CD8+ and CD45RO+ lymphocytes were much lower, while median FOXP3+ cell infiltrates were higher in recurrent samples compared with diagnostic samples." (PMID 29137242, 2017). "Focusing on TNBC, HDACi up-regulated PD-L1 and HLA-DR on tumor cells when co-cultured with PBMCs and down-regulated CD4+ Foxp3+ Treg in vitro." (PMID 29371976, 2017). "In our own studies, Treg ablation in the methylcholanthrene (MCA) carcinogen-induced fibrosarcoma mouse model of carcinogenesis resulted in profound activation of Foxp3− CD4+ and CD8+ T cells and an overall highly significant reduction in tumor growth rate." (PMID 29312327, 2017). "IDO-expressing tumor cells secrete tryptophan metabolites like kynurenines, suppressing cytotoxic effector functions via downregulation of TCR CD3 ζ-chain and induce FOXP3+ Treg differentiation." (PMID 28337200, 2017). "Further studies showed that tumor-infiltrating Tregs, defined as CD8+ FoxP3+ cells, suppressed naive T cell proliferation mainly through a cell contact-dependent mechanism." (PMID 28292326, 2017). "Tumor cells and PBMCs co-cultured or cultured individually were evaluated by flow cytometry with a multiparameter panel to assess CD45, CD3, CD4, CD8 and Foxp3 expression." (PMID 29371976, 2017). "We found that, in tumor tissues, the proportion of GARP+ cells in Foxp3+ Tregs [9.090% (3.830%, 27.20%)] was remarkably higher than that in Foxp3− Tconvs [0.2410% (0.1440%, 0.4610%), P < 0.0001]." (PMID 28261204, 2017). "Foxp3 and IL-17 were present in TIL, tumor cells and fibroblasts; IL-17 was expressed also in periendothelial cells." (PMID 27866241, 2017). "The tumor-promoting effects of MSCs were accompanied by a marked increase in CD4+ cells, CD11b+ cells, CD4+Foxp3+ Tregs, and CD11b+Ly6C+Ly6G− MDSCs." (PMID 29029511, 2017). "Thus, IL-21 should be effective regardless of whether intra-tumoural Treg are actively recruited natural Treg, in which case it would target their survival and function, or are induced within the tumour microenvironment, in which case it would target FOXP3 expression in naïve T cells." (PMID 28239749, 2017). "We also report that FOXP3 interacts with NFκB, then inhibits expression of NFκB downstream target gene COX2, and exerts the influence on inhibiting tumor cells." (PMID 28591725, 2017).
tumor (continued). "In contrast, tumour infiltration by CD4+ regulatory T cells (Tregs), which constitutively express the transcription factor forkhead box protein 3 (Foxp3) and negatively regulate immune responses, is often associated with poorer clinical outcome." (PMID 28177891, 2017). "We found both factors had an upwards trend upon recurrence; we next separated tumor-infiltrating T cells into perivascular and intratumoral CD3+, CD4+, CD8+, and Foxp3+ T cell subsets." (PMID 29163521, 2017). "Of note, MSCs induced greater infiltration of immune and immune-regulatory cells near tumor: CD4+ cells, CD11b+ cells, CD4+Foxp3+ regulatory T cells and CD11b+Ly6C+Ly6G− myeloid-derived suppressor cells." (PMID 29029511, 2017). "Our tissue microarray data showed that high expression of FOXP3 in tumor tissue significantly correlated with low serum AFP level, absence of vascular invasion and early TNM stage, suggesting a negative regulatory role of FOXP3 in HCC progression." (PMID 28903735, 2017). "We found that perivascular Foxp3+, and CD4+ T cells in the primary tumors correlated with tumor blood vessels." (PMID 29163521, 2017). "The histologic analysis revealed a linear relationship between tumor necrosis and an increased ratio of intratumoral CD8+ T cells to FOXP3+ Tregs." (PMID 28275576, 2017). "In summary, this study showed that there were more frequent tumor-infiltrating CD8+ and Foxp3+ cells in EBVaGC, which predicted a better OS in this subpopulation." (PMID 28978018, 2017). "A low ratio of tumour-infiltrating CD8+ and FOXP3+ lymphocytes is increasingly being recognised as a measure of immune suppression and as a potential prognostic indicator." (PMID 28961847, 2017). "However, it is important to note that some of these Treg might well be recruited natural Treg and that FOXP3-inducing factors within the tumour microenvironment would be continually expressed, and would, therefore, likely be sufficient to maintain stable FOXP3 expression in this setting." (PMID 28239749, 2017). "Among CD4+ T cells, both CD4+ Teffs (CD4+ FoxP3−) and Tregs (CD4+ FoxP3+) infiltrated the tumour and uninvolved pancreatic tissue in equal relative proportions in both tumours and uninvolved tissue." (PMID 28447602, 2017). "Here, we used FOXP3-transactivated cell surface protein, CTLA4, as a definitive phenotypic signature for tumor-CD8+ Treg cells." (PMID 28487507, 2017). "Thereby, we focused on the distribution and phenotype of Foxp3+ Tregs and CD8+ T cells which play an important role in tumor immunity." (PMID 28938014, 2017). "However, the FOXP3 gene may also act as a tumor suppressor in cancer models." (PMID 28603524, 2017). "Foxp3+, CD4+, and CD8+ T cells in tumoural and stromal areas were evaluated by immunohistochemistry." (PMID 28322245, 2017). "Only seen in ER- cell lines, PD-L1 up-regulation was associated with increased HLA-DR tumor cells expression, CD4+ Foxp3+ CTLA-4high Treg down-regulation in vitro, increased T cells tumor infiltration, longer survival and tumor growth inhibition in vivo." (PMID 29371976, 2017). "FoxP3+ Tregs are highly enriched in the TME and are considered to be a pivotal mediator of immune suppression, therefore facilitating tumor progression." (PMID 29088871, 2017). "To have a more complete picture of the tumor immune microenvironment, we also evaluated the ratios (CFRs) of effector T-cells (CD3+, CD8+) to suppressor T-cells (FoxP3+), as prognostic variables." (PMID 28885584, 2017). "Tumor expression of IDO also promotes the differentiation and activation of Foxp3+ regulatory T cells [reviewed in 135] that serve to recruit myeloid derived suppressor cells." (PMID 28239463, 2017). "This study provides significant information on TIL subsets, such as CD3+, CD4+, CD8+, and Foxp3+, and indicates that they can be used as prognostic biomarkers for HCC or as targeted molecules for anti-tumor treatment." (PMID 28790445, 2017).
tumor (continued). "FOXP3 can act as a co-activator to facilitate the Wnt-b-catenin signaling pathway, inducing EMT and tumor growth and metastasis in NSCLC." (PMID 28716029, 2017). "Tumor microenvironment contains the infiltration of tumor-promoting immunosuppressive cells such as TAMs, CD4+CD25+FOXP3+ Tregs, and MDSCs, which are necessary for tumorigenesis." (PMID 28143527, 2017). "For example, dendritic cells (DCs) can capture and present antigens released by tumor cells; effector T cells (CD8+) and TAMs can dissolve and devour tumor cells; and helper T cells (CD4+), including FoxP3 Tregs, impose restrictions on immune response." (PMID 28977947, 2017). "We isolated IL-17A-producing Foxp3neg, IL-17A-producing Foxp3+ and IL-17Aneg Foxp3-expressing CD4+ T cells and injected the Th17 and Treg subsets in Cd45.1 tumour-bearing mice on days 5, 12 and 19 (n=4 per group)." (PMID 28290453, 2017). "Utilizing those schedules, DTA-1 addition enhanced tumor protection/regression and those effects were attributed to enhanced costimulation of CD4+FoxP3- and CD8+ effector T cells with the simultaneous inhibition of Treg suppression." (PMID 29088720, 2017). "Of the two MPNST samples obtained at the same time from within the same tumor 12 years after original diagnosis, the low-grade sample exhibited much higher CD8+, CD4+, FOXP3+, CD45RO+, and CD56+ lymphocytic infiltrates than did the high-grade MPNST sample." (PMID 29137242, 2017). "RKO cells were found to induce the greatest expression levels of FOXP3 in naïve CD4 T cells, and blockade of TGFβ abrogated this effect, confirming the importance of this cytokine for tumour-mediated Treg induction in humans." (PMID 28239749, 2017). "PD-L1 expression in tumor cells was positively correlated with the numbers of CD3+, CD4+, CD8+, and FoxP3+ TILs (P = 0.027, P = 0.037, P = 0.003, and P = 0.006, respectively), but not with PD-1+ TILs or CD20+ TILs (P > 0.05)." (PMID 29029502, 2017). "The study reported an increase in tumor specific CD8+ lymphocytes along with a decrease in CD4+FoxP3+ regulatory T-cells and CD8+FoxP3+ T-suppressor cells." (PMID 28944214, 2017). "Our results also suggest that the transcriptional regulation of FOXP3 is controlled by three transcription factors, SMAD3, GATA3, and RUNX3, in a concerted manner involving CNSs and promoter regions of FOXP3 in tumor-induced CD8+ Treg cells." (PMID 28487507, 2017). "In accordance with their well-defined immunosuppressive role, the recruitment of Foxp3+ Tregs and myeloid derived suppressor cells (MDSCs) to TLSs within B16 melanomas engineered to express CCL21 led to promotion of tumor growth." (PMID 29312327, 2017). "With tumor TNM stage advanced, less CD4+, CD8+ and Foxp3+ cell infiltration and PD-1 expression was found in the complete cohort." (PMID 28978018, 2017). "In this study, the expression of FOXP3 was detected in HCC cell lines and tumor tissues, although the expression was obviously lower than CD4+CD25+ cells." (PMID 28903735, 2017). "We observed CD3+ T cells, CD20+ B cells and CD68+ monocytes/macrophages as well as Foxp3+ Treg cells and CD163+ TAMs to be present in peri- and intra-tumor areas." (PMID 29190964, 2017). "Within the tumor microenvironment of mGITRL-FP-treated CEA.Tg mice, a significant reduction in the percentage of Ki67+/CD44+ CD4+FoxP3- T cells was found, while the frequencies of both CD4+FoxP3+ and Ki67+/CD44+ CD8+ T cells trended downward." (PMID 29088720, 2017). "The results for the combined image confirmed that the CD4+ CD8+ cells all expressed FOXP3; in addition it was noted that many CD4−CD8− tumour cells were also FOXP3 positive [in agreement with the extensive staining seen in fixed tissues]." (PMID 27160146, 2016). "Tumour infiltrating lymphocytes (TILs: CD3+, CD4+, CD8+ and FOXp3+) were assessed by immunohistochemistry using tissue microarrays in a contemporary and homogeneous cohort of OAC patients (n = 128) undergoing curative treatment." (PMID 27020682, 2016).
tumor (continued). "CD69+ cells were increased in the tumor cell area in CD4+ and CD8+ T-cells, while FoxP3+CD25+CD4+ Tregs and CD25+CD8+ T-cells were significantly increased outside the tumor area." (PMID 27999289, 2016). "In NSCLC, tumor cells secrete the cytokine TGFβ, which promotes maturation of Treg cells into the CD25+FOXP3+ phenotype 22, contributing to immune quiescence." (PMID 27416962, 2016). "Remarkably, when cocultured with splenocytes in vitro, GMPs stimulated a significant proportion of CD4 T cells to become Foxp3+CD25+ cells, and a higher level of induction was detected with cells from tumor-bearing mice (T-GMP) than those from normal mice." (PMID 26979287, 2016). "In fact, it has been reported that MM microenvironment support overexpression of FOXP3 and CTLA4 expression in bone marrow, thus suggesting an accumulation of immunosuppressive Tregs in the tumor microenvironment of MM patients." (PMID 27493974, 2016). "Several other studies have suggested that the immune response of tumor cells can be modulated by fludarabine, paclitaxel and cyclophosphamide, by decreasing or depleting CD4+CD25+Foxp3+ Tregs." (PMID 27389040, 2016). "We performed double stainings for CD8+ CTL and FoxP3+ cells in pre-RCT biopsies and in post-RCT tumour sections." (PMID 27494875, 2016). "Both naringenin and 1D11 treatments significantly reduced the percentage of CD4+CD25+Foxp3+ and CD103+CD4+Foxp3+ cells in the lungs and spleens, respectively, of 4T1/TGF-β1 tumor-bearing mice (P <0.05)." (PMID 27036297, 2016). "We also examined the effects on tumor-promoting markers related to Treg cells, including CCL22, CXCL12 and FoxP3." (PMID 26956047, 2016). "It has been documented that tumor cells can induce Tregs in the tumor microenvironment by secreting soluble factors such as TGF-beta, VEGF and GM-CSF, which convert tissue infiltrating CD4+ T cells to Foxp3+ Treg." (PMID 27793053, 2016). "FOXP3+Tregs appear normally in the bronchial epithelium but richly gathered in NSCLC cells and tumour‐infiltrating lymphocytes." (PMID 26968871, 2016). "PD-L1 expressions in tumor cells (TCs) and TIICs, as well as infiltration of lymphocytes (CD4+, CD8+, FOXP3+, and PD- 1+) and macrophages (CD68+ and CD204+), were evaluated." (PMID 27322149, 2016). "In several of these models, B cells inhibit T cell mediated tumor immunity and/or facilitate conversion of T cells to CD4+CD25+FoxP3+ T regs, which act to attenuate the innate and/or adaptive antitumor immune response." (PMID 27437104, 2016). "We demonstrated a significant reduction of FOXP3+(intratumoural, stromal) and CTLA-4+T cells (stromal) in tumours following 8 cycles of NAC." (PMID 27777963, 2016). "Despite the lack of clinical significance for FOXP3+ Tregs alone, their combination with CD8+ TILs (CD8+/FOXP3- vs other) further enhanced the prognostic value of CD8 in our series, which supports the notion that Tregs can contribute to tumor progression." (PMID 27329602, 2016). "Initially, we compared the frequency of Tregs, defined as FoxP3+CD25+CD4+ cells, in the blood vs tumor in SCCHN patients." (PMID 27195113, 2016). "There was a significant reduction in the proportion of regulatory T cells (CD25+FoxP3+) among CD4+ T cells, which are considered deleterious in cancer by suppressing active anti-tumor immunity." (PMID 27463016, 2016). "Tumor and spleen-derived CD4+Foxp3+ Treg cells obtained from anti-TGF-β-treated IL-10−/− B16/F10 mice were significantly increased." (PMID 27075020, 2016). "The typical immunosuppressive tumour environment is characterised by a strong induction by CD4+, CD25+, FOXP3, and tumour-infiltrating regulatory T cells, and the activation of Th2 and Th17." (PMID 26913068, 2016). "Tumor-infiltrating lymphocytes dissociated from the tumors were stained with anti-CD4, anti-CD8, anti-Foxp3 and anti-IFN-γ antibodies, and then analyzed by flow cytometry." (PMID 27284967, 2016).
tumor (continued). "Immune cells in secondary tumours were collected for further analysis after co-staining with CD4 and Foxp3." (PMID 27767031, 2016). "Another study reported that FoxP3−LAP+ TI Tregs isolated from tumour tissue exhibited potent in vitro suppressive activity mediated by TGF-β and IL-10, and were up to 50-fold more suppressive than ‘conventional' FoxP3+ Tregs." (PMID 26885615, 2016). "The presence of TILs in tumor microenvironments, increased PD-L1 expression on immune cells, and the ratio of effector CD8+ T cells to FoxP3+ regulatory T cells in tumors are some examples of markers for clinical outcomes." (PMID 27234522, 2016). "TGF-β also mediates the production of mitogenic growth factors, which stimulate tumor cell proliferation and survival, and stimulates the conversion of CD4+CD25- T cells to CD4+CD25+Foxp3+ regulatory T-cells, which suppresses host immune surveillance." (PMID 27863384, 2016). "In contrast, in tumor-bearing control mice and mice treated only with anti-CTLA-4 where tumor burden was high, ICOS expression was increased on both FoxP3+ Tregs and FoxP3− Teff cells." (PMID 26961085, 2016). "Tumor cells escape immune surveillance by creating an immunosuppressive microenvironment, which includes the recruitment or generation of CD4+FOXP3+ Treg cells and/or conversion of effector T cells into Treg cells." (PMID 28123897, 2016). "The number of CD4+, CD8+, CD25+, FoxP3+ and CD20+ TILs in the late phase of tumor development (pT3–pT4) was significantly lower compared to that observed for less advanced tumors (pT1–pT2)." (PMID 26927070, 2016). "In early tumor stages, Th1 cells are the dominant population of CD4+ T cells, perhaps important for immunosurveillance; while in the advanced tumor stages, FoxP3+ Treg and Th17 cells become the dominant populations." (PMID 25968569, 2015). "Foxp3 + CD4+, CD4+ and CD8+ T cells in tumor stroma and islets were evaluated immunohistochemically." (PMID 26604855, 2015). "When stratifying for FOXP3-positive region, the pooled HR for DFS was 2.55 (95% CI: 1.23–5.30) in tumor cells, 1.46 (95% CI: 0.91–2.35) in intratumoral lymphocytes, and 1.57 (95% CI: 0.48–5.12) in peritumoral lymphocytes." (PMID 26305693, 2015). "In the case of CXCR3, although we found that a greater proportion of Foxp3+ T cells, compared with Foxp3– T cells, expressed CXCR3 in tumours, CXCR3 was more prevalent on both cell types when comparing tumours to lymph nodes." (PMID 25495686, 2015). "Focusing on the subsets of TIL, the tumor-related immune system has two paradoxically functional components: cytotoxic CD8+ T cells and regulatory FOXP3+ T cells." (PMID 26341640, 2015). "Ultimately, FOXP3-induced miR-146a/b inhibited NF-κB activation by repressing IRAK1 and TRAF6, which led to tumor suppression and apoptosis during tumor initiation in breast and prostate epithelial cells." (PMID 26682271, 2015). "The expression of genes in tumours was low for CD3Z, CD8, CXCL13, SNAI2 and ESR1 (40-DCq <32) and moderate for IGHM, CD4, CXCL9 and FOXP3 (40-DCq 32–35)." (PMID 25970543, 2015). "Systemic induction of Tregs was also observed clinically, as CD4+CD25+FoxP3+CD127 low cells were markedly increased in the peripheral blood of NHL patients and correlated with tumor burden." (PMID 25941795, 2015). "Similar findings were found in glioblastoma tumours, where all tTregs (CD4+FoxP3+Helios+) were GITR+." (PMID 25961057, 2015). "The present study investigated the prognostic significance of T cell subset (CD8, CD45RO, and FOXP3) densities using TMA cores and compared the difference between the tumor center and the invasion front of CRC." (PMID 25875774, 2015). "GR-1/CD11b-myeloid cells, CD4, MHCII, FOXP3 and vitamin D receptor (VDR)-positive Treg cells were diminished in the tumor microenvironment surrounding microscopic BCCs." (PMID 26413810, 2015).